APC (APC regulator of Wnt signaling pathway)
Diseases named in the same sentence as APC in open-access papers (continued):
Sharing a sentence is not in itself a finding about the gene and the disease.
colorectal cancer (continued). "For instance, SMAD4 loss alone may not initiate tumor formation but can promote tumor progression initiated by other genes, such as KRAS activation in pancreatic ductal adenocarcinoma and APC inactivation in colorectal cancer." (PMID 38666907, 2024). "The mutual exclusivity of RNF43 and APC mutations observed in the current report was previously reported in colorectal cancer in a report that did not examine CDX2 suppression." (PMID 39452477, 2024). "In colorectal cancers, APC alterations in the Wnt/β-catenin pathway were mainly observed." (PMID 38672586, 2024). "APC regulates WNT (wingless-related integration site) pathway signaling and has been implicated in FAP, an autosomal dominant genetic condition that typically leads to colorectal cancer if left untreated." (PMID 39507544, 2024). "Whether inhibition of LRP6 can affect APC-inactivated colorectal cancer cells is still being debated, although it is agreed that its activation can enhance downstream signaling." (PMID 38761292, 2024). "Additionally, the POP112 line did not harbour mutations or deep amplifications or deletions in the WNT pathway members defined as colorectal cancer drivers APC, AXIN1, AXIN2, CTNNB1, GSK3B or RNF43, and only a shallow deletion in ZNRF3." (PMID 38324534, 2024). "APC mutant colon cancer organoids are characterized by upregulated PTK7 expression, suggesting that PTK7 targeting may be beneficial for APC mutant colorectal cancer patients." (PMID 39474113, 2024). "Most colorectal cancers develop in the epithelium as a consequence of genetic and/or epigenetic alterations that activate the Wnt pathway, largely through the inactivation of the APC gene." (PMID 39093890, 2024). "The APC protein is a tumor suppressor that regulates the Wnt signaling pathway through the formation of complexes with various other proteins, and plays a role in the early stages of colorectal cancer development." (PMID 39336163, 2024). "In colorectal cancer and spontaneous colorectal cancer, these mutations can be discovered in genes that are involved in the APC/β-catenin/Tcf pathway, even in patients without APC mutations." (PMID 39031216, 2024). "The most frequently mutated gene of the WNT/β-catenin pathway in colorectal cancers, APC was more often mutated in the non- CDX2-suppressed group (85% of the cases) compared with the CDX2-suppressed group (APC mutations in 40% of cases, Fisher’s exact test p < 0.0001)." (PMID 39452477, 2024). "The low frequency of APC and BRAF mutation in our series is in keeping with the findings of others and supports the concept that these genes are mutated rarely in pseudomyxoma peritonei, in contrast to colorectal carcinomas." (PMID 39435876, 2024). "Phenotypic characteristics, like adenoma count, age at first adenoma and personal history of colorectal carcinoma did not significantly differ between the patients with (cases) and without (controls) APC variants fitting colibactin mutational signatures." (PMID 38238650, 2024).
colorectal cancer (continued). "The APC gene, initially identified as a mutated gene in familial adenomatous polyposis coli (FAP), is also detected in 80% of colorectal adenomas and colorectal carcinomas (CRCs), positioning it as one of the earliest mutations in the development of colon cancer." (PMID 38886806, 2024). "BHD may predispose patients to colorectal cancer because of folliculin’s role in AMPK/AKT/mTOR signaling and its inhibition of LDHA, synergizing with the more familiar APC pathway through established intermediaries of cell growth." (PMID 36859772, 2023). "A study on colorectal cancer showed that DNMT1 overexpression is associated with promoter methylation of WNT pathway regulators that include WNT inhibitory factor-1 (WIF1), adenomatous polyposis coli (APC), and Dickkopf-3 (DKK3)." (PMID 36765652, 2023). "APC is a colorectal cancer gene that is dysregulated at both the germline and somatic levels." (PMID 38004598, 2023). "We categorized tumors with APC wild-type and BRAF or KRAS mutation as serrated, a subtype of colorectal cancer that derive from serrated polyps via an alternate pathway usually with absence of APC mutation." (PMID 37057593, 2023). "The previous report showed that pACC has genetic mutation in APC /ß-catenin which tend to be found in colorectal cancer, not in PDAC." (PMID 37610633, 2023). "In CRC (Colorectal Cancer), APC and SMAD4 are also identified as the candidates." (PMID 38062391, 2023).
colorectal cancer (continued). "By combining bioimaging and genetic tools with artificial intelligence algorithms applied to colorectal cancer cell, we found that the APC-dependent actin pool contributes to sustaining levels of F-actin, as well as E-cadherin and occludin protein levels at cell junctions." (PMID 37128612, 2023). "Inactivation of APC promotes nuclear accumulation of β-catenin and may trigger colorectal cancer (CRC)." (PMID 36934880, 2023). "The three-hit model has shown to be applicable in APC in colorectal cancer, and it can be speculated whether this same model could be applicable for YEATS4 and DMAP1 in case of mutations with possible residual activity." (PMID 36773604, 2023). "APC has long been known to be an important initiator gene for the majority of colorectal cancers." (PMID 35359365, 2022). "In colorectal cancer, a loss-of-function mutation in APC is very common, stabilizing β-catenin due to the lack of destruction complex." (PMID 35359365, 2022). "APC I1307K has a two-fold increased risk for colorectal cancer in Ashkenazi Jews (AJ) compared to non-Jewish populations." (PMID 36497357, 2022). "There may be a link between SCG2 and APC in the development of colorectal cancer, making SCG2 play an essential role in disease progression." (PMID 35844556, 2022). "In a ‘three-hit’ hypothesis it has been stated that in some colorectal cancers Wnt signaling is modulated by copy number changes or other ‘third-hits’ of APC." (PMID 36230711, 2022). "An additional key observation of the current report is that BRAF mutated colorectal cancers with or without PIK3CA mutations display lower prevalence of APC mutations than colorectal cancers with wild type BRAF." (PMID 36079062, 2022). "APC protein deficiency results in β-catenin accumulation in the cytoplasm; this leads to sustained transcriptional activation of TCF-mediated genes and promotes colorectal cancer progression." (PMID 35975176, 2022). "We identified ELOF1and CAB39 as novel nuclear β-catenin accumulation regulatorsand devised a novel sorting strategy that could be leveraged to target APC-mutant colorectal cancer." (PMID 36589880, 2022). "As far as we can find, there are three cases with HER2 G776S mutation in the COSMIC database, but these cases are not colorectal carcinoma and do not have APC mutation." (PMID 35654814, 2022). "Thus, the APC-Asef interaction has attracted considerable interests as a highly enticing target for colorectal cancer therapy exploiting PPI inhibitors." (PMID 34017824, 2021). "A better understanding of both genetics and biological function of APC may help develop preventive or therapeutic regimes that aim to reduce the burden of colorectal cancer over time." (PMID 33237662, 2021). "Variants in genes associated with colorectal cancer accounted for the highest percentage of reported alleles (including moderate impact heterozygous MUTYH variants and APC increased risk alleles), followed by variants in genes associated with breast cancer, breast and ovarian cancer, and melanoma." (PMID 34404389, 2021). "The majority of colorectal cancers harbor loss-of-function mutations in APC, a negative regulator of canonical Wnt signaling, leading to intestinal polyps that are predisposed to malignant progression." (PMID 33525395, 2021). "Similarly, in colorectal cancer, Notch1 signaling retained the capabilities of suppressing the expression of Wnt target genes, even when B-Catenin destruction by APC complex was disabled." (PMID 33968932, 2021).
colorectal cancer (continued). "Their regular consumption showed to exacerbate colorectal tumor development in a preclinical model of colitis-induced colorectal cancer, and to aggravate the initiation and development of genetically driven CRC, as demonstrated in mice mutated for the tumor suppressor gene APC." (PMID 34885046, 2021). "A deleterious mutation in RNF43 has been reported in 19% of colorectal cancers lacking APC mutations." (PMID 34552611, 2021). "In this way, the model can mimic the development of colorectal cancer in which a normal intestinal cell subjected to APC impairment initiates uncontrolled cell proliferation that, together with interactions with the intestinal microenvironment, ultimately leads to the development of cancer with ITH." (PMID 34548081, 2021). "Mutation in the serine/threonine regulatory domain of β-catenin has been found in 48% of colorectal cancers lacking APC mutations." (PMID 34552611, 2021). "We attempted to identify new driver mutations as well as validate existing drivers using validated calling algorithms; however, only APC was consistently enriched across all four callers in our study, once again emphasising the predominant Wnt signalling driven nature of colorectal cancer." (PMID 33632293, 2021). "Adenomatous polyposis coli (APC) mutation is referred as an initiator of colorectal cancer, it frequently occurred (81%) in the non-hypermutated colon and rectum cancer." (PMID 33406731, 2021). "While WNT-signaling alterations start with APC mutations in about 70% of colorectal cancer patients, mutations are not the major cause of these deregulations in melanoma." (PMID 32659938, 2020). "Chemical inhibition of COX-2, as well as the deletion of the COX-2 gene or various PGE2 receptors, was found to dramatically decrease intestinal polyp formation in numerous mouse models of colorectal cancer, including APC mutant mice and mice exposed to carcinogens." (PMID 32325966, 2020). "Indeed, APC undergoes phosphorylation during mitosis by human p34(cdc2)-cyclin B1 in HCT116 colorectal cancer cells." (PMID 33348689, 2020). "c-Myc is a target of APC signaling, which aberrantly activated in most colorectal cancers." (PMID 32258125, 2020). "Neither colon syngeneic model has an APC mutation, which is mutated in the majority of human colorectal cancer and neither the breast-derived tumor model EMT6 nor 4T1 have activating mutations in PIK3CA." (PMID 31898484, 2020). "Here, we review our current understanding of APC inherent activities and partners in order to explore novel avenues by which APC may act as a gatekeeper in colorectal cancer and as a therapeutic target." (PMID 33348689, 2020). "It has therefore been proposed that truncated forms of APC often found in colorectal cancer are not only deleterious due to unregulated β-catenin accumulation but may also enhance cellular metastasis due to constitutive Asef activation." (PMID 32178475, 2020). "In colorectal cancers, the CDKN2A, CDK4/6, Rb signaling cascade might also control tumourigenesis driven by loss of wild type APC function." (PMID 30655555, 2019). "Degradation of β-catenin can be analyzed by expression of negative Wnt/β-catenin signaling regulators in SW480 colorectal cancer cells, which harbor high β-catenin levels due to APC mutations." (PMID 31534175, 2019). "APC mutation occurs in 81% of non-hypermutated colorectal cancers cases and in 51% of hypermutated colorectal cancer cases, triggering tumorigenesis in intestinal polyps of patients with familial adenomatous polyposis." (PMID 31817828, 2019).
colorectal cancer (continued). "Neither APC nor KRAS mutations alone induce a colorectal cancer phenotype, although APC mutations also induce RAS activation through inactivation of glycogen synthase kinase 3β (GSK3β)." (PMID 30717152, 2019). "Thus, overexpression of CD44v6 associates with colorectal cancer in advanced stages and is characterized by mutations in the WNT pathway (e.g., APC mutations)." (PMID 31921125, 2019). "APC T1160K appeared in colorectal cancer for 2 out of 6 samples it was found." (PMID 30709382, 2019). "In addition, APC play a rate-limiting role in most sporadic colorectal cancers, particularly by impinging on the WNT pathway." (PMID 30642111, 2019). "To better understand what could drive sensitivity to MSC2504877, we carried out parallel RNA interference (RNAi) and small molecule/drug high-throughput chemosensitisation screens using MSC2504877 in APC mutant colorectal cancer tumour cell lines." (PMID 30655555, 2019). "Hence, describing the novel canonical Wnt signaling pathway inhibiting small molecules that act downstream to APC is a recurrent strategy to improve colorectal cancer treatability." (PMID 31817828, 2019). "To explore the underlying mechanism mediating this effect we initially investigated cell growth in COLO320DM (APC mutated/KRAS WT) and HCT-15 (APC mutated/KRAS mutated) colorectal cancer cells under the influence of 1 μM G007-LK (TNKS inhibitor; TNKSi) and/or 1 μM GDC-0973 (MEK inhibitor; MEKi)." (PMID 30717152, 2019). "According to a research in 2017, β-catenin can be deubiquitinated and stabilized by USP7 in adenomatous polyposis coli (APC) truncating mutated colorectal cancer (CRC) but not APC wide type CRC, which resulting in the activation of Wnt pathway." (PMID 31114498, 2019). "Along with SMAD4, APC is another important gene in colorectal cancer." (PMID 30709382, 2019). "In colorectal cancer, it appears that loss of ARID1A in wild-type backgrounds may promote early tumorigenesis while loss of ARID1A in the background of mutations in APC or KRAS may inhibit tumor progression." (PMID 31217031, 2019). "Interestingly, this was evident not only in well‐characterized driver genes such as PTEN in endometrial cancer and APC in colorectal cancer but also in recurrent, clonal driver mutations that are rarely found in that tumour type." (PMID 29604063, 2018). "The authors first show that inhibition of LRP6 in colorectal-cancer cell lines (CRCs) carrying mutations in APC, or in cells lacking APC by CRISPR-mediated knockout, reverses β-catenin signaling." (PMID 29533767, 2018). "Mutations in APC trigger this tumor-initiating step, underlying both the hereditary cancer syndrome, termed familial adenomatous polyposis (FAP) and the majority of sporadic cases (approximately 85%) of colorectal cancer." (PMID 29615557, 2018).